INS (insulin)
Diseases named in the same sentence as INS in open-access papers (continued):
Sharing a sentence is not in itself a finding about the gene and the disease.
diabetes (continued). "For example, direct infusion of leptin, insulin, and fibroblast growth factors into the brain exhibits a remarkable antidiabetic effect in animal models of diabetes." (PMID 33974562, 2021). "STZ induces diabetes by damaging the pancreatic beta cells, reducing insulin secretion and uptake of glucose by the tissues." (PMID 34656137, 2021). "The average HbA1c was 9.1% (SD 1.7%) with a mean of 15 years of diabetes duration, and 60% of the participants were insulin-dependent." (PMID 33427667, 2021). "Under pre-diabetes and diabetes scenarios, the high demand for insulin production is accompanied by an increase in IAPP expression." (PMID 34959837, 2021). "Patients were asked to rate COVID-19-like symptoms, psychological symptoms, epidemiological issues, and adherence to diabetes management (insulin, exercise, and diet) using a 0-to-10 scale." (PMID 33166438, 2021). "FA also stands out for its effects in diabetes control at various levels: reducing blood glucose through inhibition of α-glucosidase and improving insulin secretion in diabetic rat models and in pancreatic cells." (PMID 34574099, 2021). "Diabetes mellitus (DM) is a group of metabolic disorders that have in common the chronic hyperglycemia, which results from defects in insulin secretion, insulin action, or both." (PMID 33815273, 2021). "The secondary goal is to offset the development of diabetes with the potential for patients to become independent from exogenous insulin (islet autotransplantation)." (PMID 34064129, 2021). "Despite significant advancements in insulin and related diabetes technology, a minority of patients with T1D are meeting the glycemic targets known to reduce complications." (PMID 37745178, 2021). "Type 1 DM patients are characterized by destruction of insulin-producing pancreatic beta-cells and type 2 diabetes mellitus (T2DM) patients with lowered response to insulin." (PMID 34372916, 2021). "Briefly, long-term increases in the plasmatic levels of leptin or insulin, resulted in insulin or leptin resistance, paving the way to diabetes or fat accumulation." (PMID 33574566, 2021). "In particular, Caucasian veterans and veterans who require insulin are more likely to demonstrate improved glycemic control with improved diabetes distress." (PMID 33427667, 2021). "Patients in the conventional arm received their baseline diabetes medications (including subcutaneous insulin); additional short-acting subcutaneous insulin was permitted for those with a glucose level >288 mg/dL (16 mmol/L)." (PMID 33466656, 2021). "Future studies need to unravel involved mechanisms and develop potential novel treatment approaches for impaired insulin secretion in diabetes." (PMID 34645853, 2021). "Type 1 diabetes mellitus (T1DM) is an autoimmune disease that results from the destruction of the pancreatic beta cells producing insulin." (PMID 33445500, 2021). "Here, we report a peculiar case report of an adverse events related to insulin pen use in a type 2 diabetes mellitus patient." (PMID 33492465, 2021). "Its molecular size and susceptibility to conformational change under physiological pH make it challenging to orally administer insulin in diabetes." (PMID 34959394, 2021). "“my mom has diabetes worse than me...just seeing what she has to do every day, which is take shots, it’s just something I don’t want to do, I don’t want to be on insulin.”." (PMID 34699536, 2021). "We found that lack of PRLR signaling increases the prevalence and severity of STZ-induced diabetes by enhancing β-cell dysfunction (reduced proliferation, survival, and insulin production)." (PMID 33746901, 2021). "Lee and colleagues also examined in a further study the effect of insulin therapy on HF outcomes in patients with diabetes (KorAHF registry)." (PMID 34740359, 2021).
diabetes (continued). "Glulisine (APIDRA) is a rapid-acting human insulin analogue indicated to improve glycaemic control in adults and paediatric patients, who present with diabetes mellitus, a condition which results from metabolic aberrations." (PMID 33462295, 2021). "Type 2 diabetes mellitus (T2DM) is a complicated disease marked by a decrease in insulin function that will follow a decreased release of insulin from ß cells (pancreatic ß-cell dysfunction)." (PMID 34527070, 2021). "In many cases, the patients with diabetes mellitus had issues with a suboptimal effect of oral antidiabetics and/or insulin; mainly, patients had elevated or fluctuating blood glucose levels." (PMID 34449695, 2021). "In the last 20 years, there has been incremental improvement in terms of technology for diabetes: disposable insulin pens, improved glucometers, insulin pumps and continuous glucose monitoring technology (CGM) among them." (PMID 34372462, 2021). "Patients evolve with hypertriglyceridemia, severe insulin resistance and poorly controlled diabetes, that usually require extremely high doses of insulin." (PMID 34130736, 2021). "PPARγ is the molecular target of thiazolidinediones (TZDs), drugs used as insulin sensitizers to treat type 2 diabetes mellitus." (PMID 34071972, 2021). "The fuzzy logic approach modulates insulin delivery based on approximate rules to express empirical knowledge of diabetes practitioners." (PMID 33550442, 2021). "Patients with CGL and DM usually require higher doses of insulin (>2 IU/Kg/d), as we can see in most (4/6) of our patients with diabetes." (PMID 34033296, 2021). "At present, traditional drugs for the treatment of diabetes are mainly insulin secretion and insulin sensitization, which will produce adverse reactions to patients, leading to a decline in patient compliance, leading to treatment failure." (PMID 33959665, 2021). "Assessment of diabetes, IT knowledge, adherence and perception towards diabetes were conducted using validated study tools Insulin Treatment Appraisal Scale (ITAS) and Medication Compliance Questionnaire (MCQ))." (PMID 34400860, 2021). "The gastric inhibitory polypeptide receptor (GIPR) can stimulate insulin release in the presence of elevated glucose; variants of GIPR were found linked with diabetes-related primary OAG." (PMID 33874942, 2021). "The same model of diabetes was adopted by Banting and Best32) for their historic observation on the hypoglycemic properties of a crude pancreatic extract of insulin." (PMID 34629354, 2021). "A novel index based on glucose and TG measurements (the TyG index), has shown high sensitivity and specificity for identifying participants with disturbed insulin function, as well as early diabetes onset in patients with normal fasting glucose." (PMID 34790686, 2021). "This further solidifies the multifactorial idea that age, hemoglobin A1C level, diabetes duration, insulin usages, and degree of retinopathy proliferation are all responsible for the change in VA and CMT." (PMID 33434220, 2021). "Approximately 90% of people with diabetes have Type 2 diabetes (T2D), which is characterised by defects in insulin secretion and insulin action." (PMID 34779483, 2021). "Macrophage polarization is another anti-inflammation approach for diabetes that enhances insulin sensitivity." (PMID 34163437, 2021). "Other studies have also shown that SCFAs can also improve insulin sensitivity, regulate fat and muscle energy metabolism, and play an important role in the development of diabetes and obesity." (PMID 35173696, 2021). "Reduction of IGFBP1 in diabetes through both insulin-dependent and insulin-independent pathways is a novel mechanism by which carnosine contributes to the improvement of the metabolic control in diabetes." (PMID 34203479, 2021).
diabetes (continued). "In one study examining overweight adult subjects with atypical ketosis-prone diabetes, only those with autoantibodies and evidence of β-cell function demonstrated elevations in unmethylated and methylated INS." (PMID 33670079, 2021). "The low-dose lansoprazole treatment (LDLT) decreased partially triglyceride level and increased insulin level however the high-dose lansoprazole treatment (HDLT) significantly increased insulin level compared to diabetes control group (p < 0.05)." (PMID 33641315, 2021). "In particular, the function of insulin-producing β-cells is more severely impaired in most patients with type 1 diabetes mellitus than in patients with type 2 diabetes mellitus, and those with β-cell insufficiencies require an exogenous insulin replacement." (PMID 34681566, 2021). "Diabetes mellitus is a prevalent metabolic disorder which results in the abnormal function and insulin secretion." (PMID 33952324, 2021). "Advances in diabetes technologies have enabled the development of automated closed-loop insulin delivery systems." (PMID 33550442, 2021). "Previous publications showed the potential of PCA and C3G in reducing blood glucose, enhancing insulin sensitivity, and increasing glucose uptake, thereby improving glucose homeostasis in diabetes." (PMID 34439892, 2021). "Diabetes mellitus is a group of metabolic abnormality identified by hyperglycemia resulting from defects in insulin secretion, insulin action, or both." (PMID 33806973, 2021). "Activation of PPARα has been shown to improve lipid and glucose metabolism in diabetes by reducing hyperglycemia and increasing insulin sensitivity." (PMID 34440028, 2021). "The pathophysiology of T2DM involves not only insulin resistance in peripheral tissue but also the impairment of insulin secretion capacity, particularly in the late stage of diabetes." (PMID 33916828, 2021). "Finally, the possibility of a role for CD24 in insulin sensitivity and obesity, as suggested in this study, may contribute to an improved understanding of the increasingly growing association between cancer and both diabetes and obesity." (PMID 33467499, 2021). "Chronic exposure to elevated saturated fatty acids (SFAs) of pancreatic β cells is a key trigger of impaired insulin secretion, which is one of the most important characteristics of type 2 diabetes mellitus (T2DM)." (PMID 34022799, 2021). "Hyperglycemia due to diabetes, tissue resistance against insulin, hyperinsulinemia accompanied with insulin tolerance, and obesity, specifically visceral fat obesity, can promote arteriosclerosis in diabetes." (PMID 34871313, 2021). "MiR-204 blocks insulin production via direct targeting of Mafa, contributing to the development of diabetes, and its inhibition improves glycaemic control in db/db mice." (PMID 34803905, 2021). "Self-regulated “smart” insulin administration system that mimic pancreatic endocrine function would be highly desirable for diabetes management." (PMID 34750459, 2021). "Simultaneously, chronic HPTQ treatment debilitated diabetes-induced cognitive deficits and regulated hippocampal insulin metabolism activated CREB/BDNF/TrkB signaling pathway and suppressed the mitochondria-related Bax/Bcl-2 and caspase-3 apoptosis pathway." (PMID 34211563, 2021). "In the 1930s, Woodyatt described the combination of insulin sensitivity and hypoglycemic unawareness as “brittle” diabetes." (PMID 34067286, 2021). "Time since diagnosis and type of diabetes seemed to be related to the number of insulin positive cells and respective insulin content." (PMID 33621402, 2021). "Hypertriglyceridemia accompanies diabetes as well due to insulin-stimulated regulation of lipid flux." (PMID 34064568, 2021). "In both studies, the implantation of these functional hPSC-derived beta cells rescued diabetes in mice and had increasing levels of human insulin produced by the grafts over time." (PMID 33828531, 2021).
diabetes (continued). "Diabetes mellitus (DM) is a group of metabolic disorders which is characterized by the presence of high glucose level in the blood resulting from impairment in insulin secretion, insulin action, or both." (PMID 33974654, 2021). "Administration of insulin and oral and injectable hypoglycemic agents is the mainstay of treatment of diabetes and is effective in controlling hyperglycemia." (PMID 33467194, 2021). "Model 1, adjusted for glucose-lowering group; Model 2, additionally adjusted for baseline age, race/ethnicity, diabetes duration, HbA1c, body mass index and eGFR; Model 3, additionally adjusted for insulin and sulphonylureas use." (PMID 34879878, 2021). "Female sex, pubertal diabetes onset, long diabetes duration, lower BMI-standard deviation score at diabetes onset, intensive insulin therapy, and higher insulin dose were significant predictors of weight gain." (PMID 34638531, 2021). "The latest international guidelines for the management of children with diabetes undergoing surgery include specific adjustments to the patient's insulin therapy, hourly blood glucose monitoring, and intravenous (IV) insulin infusion." (PMID 33996680, 2021). "Diabetes mellitus belongs to the group of metabolic diseases that occur because of inadequate amounts of insulin to burn sugar, impaired insulin functioning or both." (PMID 33780148, 2021). "This acid not only increases hepatic glycogen storage, but also increases the ability of the impaired pancreas to secrete insulin in the case of diabetes." (PMID 34201697, 2021). "The primary site of insulin resistance in obesity and type 2 diabetes mellitus is the skeletal muscle, as it accounts for around 80% of insulin-stimulated glucose disposal." (PMID 34445261, 2021). "The main preoperative predicting factors for diabetic control are age, BMI, C-peptide, gender, diabetes duration, glycemic control, insulin use, and surgical procedure type." (PMID 35027968, 2021). "Some patients died unexpectedly and predictors of this type of death include male sex, insulin-treated diabetes, chronic kidney disease, and independence in activities of daily living." (PMID 33670462, 2021). "The Observational Registry for BI Treatment (ORBIT) on 19,894 patients with T2DM in China found that prior to insulin initiation, mean duration of diabetes was 6.4 ± 5.3 years and mean HbA1c level was 9.6 ± 2.0%32." (PMID 33602996, 2021). "We conducted further subgroup analyses based on the sample size, period of insulin treatment, and type of diabetes, but moderate/high heterogeneity remained in all subgroups." (PMID 34367067, 2021). "The basal and rapid-acting insulin dose was titrated at each meal and at bed-time according to the titration algorithms in 9 patients with diabetes." (PMID 33916210, 2021). "Prior to the discovery of insulin and conventional drugs, diabetics were treated with herbs and traditional medicines." (PMID 33849494, 2021). "Undoubtedly, the high concentration of KYN observed in the course of diabetes contributes to the release of insulin." (PMID 34199713, 2021). "Type 2 diabetes mellitus (T2DM), also called metabolic syndrome, is due to a progressive loss of β-cell insulin secretion frequently on the background of insulin resistance and accounts for about 90% of the total number of diabetes patients." (PMID 34899946, 2021). "Our previous study has found that LCCP app-based diabetes education is effective for glycemic control and can improve self-monitoring of blood glucose behavior in patients with type 2 diabetes receiving insulin therapy." (PMID 33544081, 2021). "It is well-known that insufficient pancreatic β cell function can lead to decreased insulin secretion, which further aggravates the development of diabetes." (PMID 34823419, 2021). "Type 1 diabetes mellitus (T1DM) is considered as a multifactorial autoimmune disease in which the islet cell immune response destroys insulin-producing β cells in the endocrine islets of Langerhans." (PMID 33880360, 2021).
diabetes (continued). "Take the following extracts from a diabetes consultation in which the doctor asks the patient to confirm that she has been prescribed NovaRapid, a quick-acting insulin that is to be taken with meals." (PMID 33519050, 2021). "In diabetes, peptide-drugs remain the dominant modality with a clear transition in focus from insulin products to incretin therapies in the recent five years." (PMID 33802091, 2021). "Impaired insulin signaling and inflammation are shared pathologies in both DM and AD highlighting the importance of Geriatricians in diabetes care in which cognitive function and compliance with the medications are essential components." (PMID 34040911, 2021). "Diabetes is classified into two types: T1DM, caused by damnification of pancreatic β cells, along with insufficient insulin secretion, and T2DM, which is mainly induced by insulin resistance." (PMID 34307381, 2021). "In our study, we enrolled MetS patients with normal glucose, prediabetes, or mild newly onset diabetes and performed a 2-year lifestyle intervention to examine its effects on insulin secretion and insulin resistance." (PMID 33490287, 2021). "Type 2 diabetes mellitus (T2DM) is the most common form of diabetes, characterized by chronic inflammation of pancreatic islets, impaired insulin secretion, and the presence of amyloidogenic aggregates." (PMID 34835247, 2021). "From the corrected PSCs derived from permanent neonatal diabetes mellitus (PNDM) patients, insulin-secreting pancreatic islet cells were generated, and upon transplantation into mice protected the mice from diabetes." (PMID 33402224, 2021). "MLN4924 also attenuates excessive ETV5 degradation, obesity, and diabetes development in ob/ob mice, improving their hyperglycemia, hyperinsulinemia, glucose tolerance, and insulin sensitivity." (PMID 33911083, 2021). "With diabetes, the body either makes insufficient insulin or defectively uses the insulin, resulting in hyperglycemia." (PMID 34697343, 2021). "Over the past several decades, numerous studies have identified type 2 diabetes mellitus (T2DM) and obesity as determinant factors associated with impaired insulin clearance." (PMID 33668109, 2021). "The anti-hypertensive effect of resveratrol that was consistently reproduced only in studies testing doses >300 mg/day was reported mainly in patients with diabetes mellitus type 2 likely due to its favorable effect on insulin sensitivity." (PMID 34660673, 2021). "Among patients receiving insulin, 6/240 (3%) scored ≥ 3 on items “I am afraid of injecting myself” and “I’m afraid to prick my finger” using the Barriers to Diabetes Questionnaire, indicating “serious problems” with needles." (PMID 34111207, 2021). "Interest for resistin as a link between obesity and diabetes originated from the observations of increased insulin sensitivity in response to reducing resistin levels in obese mice." (PMID 33716966, 2021). "Sphingolipids are complex lipids that are particularly abundant in nervous tissue and are implicated not only in a number of neurological diseases but also in insulin-resistant conditions such as diabetes or non-alcoholic steatohepatitis." (PMID 33084971, 2021). "The majority of participants (17/20, 85%) managed their diabetes with a continuous subcutaneous insulin infusion pump, with 3/20 (15%) using multiple daily injections." (PMID 34047700, 2021). "Her Hb1c, insulin autoantibodies and oral glucose tolerance test indicated her diabetes was a side effect of glucocorticoid therapy." (PMID 33731004, 2021). "Achieving glycemic targets with conventional insulin therapies is challenging forpeople with diabetes, and for people with gastroparesis there are additionalcomplicating factors." (PMID 34378426, 2021).